EGR1 (early growth response 1)
Diseases named in the same sentence as EGR1 in open-access papers (continued):
Sharing a sentence is not in itself a finding about the gene and the disease.
myopia (28 papers, 2007 to 2025). "Other neurotransmitters and signaling molecules linked with light and myopia are atropine, 5-hydroxytryptamine (5-HT), EGR-1 (ZENK), gamma-aminobutyric acid (GABA), retinoic acid (RA), melanopsin, and ipRGCs." (PMID 38297353, 2024). "The loss or reduction of function mutations of ZENK (the chicken and mouse orthologs of mammalian EGR-1) have been implicated in myopia progression." (PMID 37857760, 2023). "Overall, these results demonstrate that Prss56 inactivation rescues axial elongation/myopia resulting from EGR1 deficiency, and thereby establish PRSS56 as a potential therapeutic target for interventions aimed at preventing myopia." (PMID 29529029, 2018). "Another study revealed that EGR1, a myopia-suppressive gene, is associated with VL." (PMID 34830743, 2021). "For instance, mice with a null mutation of the transcriptional factor Egr1 recapitulate the ocular axial length elongation and refractive shift characteristic of myopia and constitute a useful animal model to dissect the mechanisms involved in ocular growth and myopia." (PMID 29529029, 2018). "Importantly, we demonstrate that genetic inactivation of Prss56 can rescue axial elongation in a mouse model of myopia caused by loss of EGR1 function." (PMID 29529029, 2018). "Therefore, it would be interesting to know if there are mutations in EGR1 of human individuals with myopia especially high myopia where excessive axial elongation of the eye is a common prominent feature." (PMID 18636116, 2008). "The expression pattern of EGR-1 aligns with the trajectory of eye growth: it is downregulated in eyes developing LIM (lens-induced myopia) and upregulated during recovery from LIM." (PMID 39720655, 2024). "Torii et al4 found that violet light (VL, 360–400 nm wavelength) suppresses myopia progression by upregulating the myopia suppressive gene EGR1." (PMID 38692719, 2024). "Up-regulated egr1 expression in 2-day normal-light-reared (∼4 wpf) efemp12C-Cas9 fish showed evidence myopia suppression, whereas down-regulation of egr1 in 4-week normal-light-reared (equivalent to 8 wpf) efemp12C-Cas9 fish showed a myopic shift." (PMID 39607017, 2024). "We observed EGR1 upregulated in 8 cell clusters in response to recovery from induced myopia, representing the most globally upregulated gene in the recovering choroid." (PMID 38390290, 2023). "In the current study, we found that this pathway regulates the expression of EGR-1, an important gene for the progression and suppression of myopia." (PMID 37857760, 2023). "To verify the possible mechanism of suppressing the progression of myopia by GBEs administration, we used real-time PCR to detect the expressions of Egr-1 and eNOS in the retina and the choroid after three weeks of GBEs oral administration." (PMID 36882511, 2023). "Several pharmacologic agents prevented the downregulation of Egr-1 mRNA expression in experimental myopia chick models such as FDM and LIM28,38,39." (PMID 37857760, 2023). "Egr-1 is a protein-coding gene that controls the axial elongation and progression of myopia, and Egr-1 knockout mice exhibited longer axial length and a myopic refraction shift, suggesting a myopia-suppression-related gene." (PMID 37857760, 2023). "Violet light suppressed the axial length elongation in the chick myopia model, and myopia suppressive gene EGR1 was upregulated as revealed by expression microarray analyses." (PMID 34016090, 2021). "Crocetin was demonstrated to have a suppressive effect on myopia progression in mice, and the expression of Egr-1, a myopia suppressive gene, was shown to be in a dose-dependent manner in vitro." (PMID 31936441, 2020). "To date, chemical compounds or light exposure increasing Egr-1 activity have been reported to suppress myopia progression in animal models." (PMID 30670743, 2019). "Among various myopia-related genes, early growth response 1 (Egr1) was shown to be upregulated by violet light exposure both in vivo and in vitro." (PMID 31394821, 2019).
myopia (continued). "Downregulation of Egr-1 was observed during experimental myopia progression in various animal species." (PMID 31795325, 2019). "In fact, violet light, which has the shortest wavelength of visible light, was demonstrated to induce Egr-1 and suppress myopia." (PMID 31795325, 2019). "Egr-1 is a transcriptional factor known as a myopia suppressive agent functioning in the feedback mechanism for axial ocular growth." (PMID 30670743, 2019). "Alternatively, our present study is the first to describe a natural extract crocetin as a myopia control agent through upregulation of Egr-1." (PMID 30670743, 2019). "In this study, we focused on Egr-117,22 as a myopia suppressive factor, and performed an in vitro screening assay with a dietary factor library using Egr-1 activity as an indicator." (PMID 30670743, 2019). "Dietary crocetin, one of the antioxidant carotenoids, was also revealed to suppress myopia through Egr-1 activation." (PMID 31795325, 2019). "To prove the suppressive mechanism of myopia progression, we examined Egr-1 mRNA expression in the retina with real-time PCR, but the results were inconsistent." (PMID 30670743, 2019). "Consistent with our ocular size findings, refraction was significantly rescued in double mutants compared to single Egr1 or Prss56 mutants, exhibiting myopia or hyperopia, respectively." (PMID 29529029, 2018). "No pathological mutations were detected upon sequencing of the coding regions and the adjacent intronic regions of EGR1 in 96 unrelated Chinese subjects with high myopia." (PMID 18636116, 2008). "EGR1 (OMIM 128990) is an early growth response gene that has been shown to be related to myopia by upregulation and down-regulation of axial eye growth in experimentally induced chicken myopia and knockout mice." (PMID 18636116, 2008). "A potential connection between Egr-1 and myopia was first described in the chick, where it was found that the expression of ZENK correlates with the sign of defocus imposed by lenses in a subset of amacrine cells (AC), specifically the glucagon AC." (PMID 17653032, 2007). "Moreover, early growth response gene type 1 Egr-1 (the human homolog of ZENK) activates the TGF-β1 gene by binding to its promoter, which is thought to be associated with myopia." (PMID 40864167, 2025). "The early growth response 1 (egr1) gene is an immediate early response transcriptional factor that has been shown to be up-regulated when the eye is exposed to hyperopia-inducing or myopia-suppressing visual environments, and down-regulated when the eye is under myopia-inducing visual conditions." (PMID 39607017, 2024). "Although further studies are needed to determine why VL exposure was the most effective in suppressing myopia progression, EGR-1 expression may be one of the reasons for this outcome." (PMID 37857760, 2023). "Additionally, GBE intake increased Egr-1 and endothelial nitric oxide synthase expression in the choroid and improved choroidal blood flow, which had decreased during myopia progression." (PMID 37857760, 2023). "We investigated natural agents that inhibit myopia based on Egr-1 activity and found that crocetin, a dietary factor, may have protective effects against myopia progression." (PMID 35619815, 2022). "We have shown that violet light (360–400 nm wavelength) suppresses axial elongation in an experimental chicken myopia model, and by expression microarray analysis, we found that the expression of the myopia suppressor gene early growth response protein 1 (Egr-1) is upregulated by violet irradiation." (PMID 35619815, 2022). "EGR1 expression was dominant in the myopia-suppressed enucleated eyes illuminated by VL in chicks." (PMID 34830743, 2021). "Dietary crocetin was demonstrated to induce Egr1, which is known as a myopia-suppressive gene." (PMID 31394821, 2019).
myopia (continued). "To explore agents which may control myopia, we screened 207 types of natural compounds and chemical reagents based on an activity of a myopia suppressive factor, early growth response protein 1 (Egr-1) in vitro." (PMID 30670743, 2019). "In addition to the most well-known hypoxia-related transcriptional factor—the hypoxia-inducible factor (HIF) —a myopia suppressive transcriptional gene Egr-1 is also upregulated by hypoxia." (PMID 31795325, 2019). "Egr-1 is reported to be a possible myopia suppressive factor which may affect axial eye growth, accompanying changes of other eye structures." (PMID 30670743, 2019). "Therefore, we selected EGR1, FOS, JUN, VIP and VIPR2 as functional candidates and investigated their potential association with high myopia." (PMID 23637909, 2013). "Therefore, it is difficult to define those genes that are responsible for the development of the relative myopia in the 42-day-old Egr-1 knockout mice." (PMID 20019881, 2009). "Apart from EGR1, myopia-like changes has been observed in lumican-fibromodulin double null mice." (PMID 18636116, 2008). "The purpose of this study was to test whether variations in the human EGR1 gene are related to high myopia." (PMID 18636116, 2008). "Upon complete sequencing analysis of the coding regions and the adjacent intronic regions, no mutation was identified in the 192 chromosomes of EGR1 in the 96 subjects with high myopia." (PMID 18636116, 2008). "Therefore, the link between VL exposure-induced EGR-1 and its possible molecular target (Opn5) pathway in the retina may be important for the development of promising myopia control strategies." (PMID 37857760, 2023). "Therefore, Egr-1 can be considered as a biological marker for myopia suppressive intervention." (PMID 30670743, 2019). "However, in human beings, sequence analysis of EGR1 did not detect any mutation in the 96 patients with high myopia." (PMID 18636116, 2008). "Thus, hyperoxia may induce downregulation of Egr-1, resulting in myopia progression." (PMID 31795325, 2019). "Recently, we screened 207 natural products utilizing a myopia suppressive gene early growth response protein 1 (EGR1) as a biomarker and found out a carotenoid crocetin has a suppressive effect against progression of myopia in a murine model." (PMID 31261724, 2019). "All of these experiments suggested that Egr-1 (ZENK) is an important factor in controlling eye growth, at least in some animal models for myopia." (PMID 20019881, 2009). "Homozygous knockout mice, lacking functional Egr-1 protein, developed relative axial myopia at the age of 42 and 56 days (compared to heterozygous and wild-type Egr-1 knockout mice)." (PMID 20019881, 2009). "The results suggest that EGR1 is unlikely to be the responsible gene for high myopia in these patients." (PMID 18636116, 2008). "The EGR1 gene is expressed in the amacrine cell of the retina and was shown to respond to optical defocus in a sign-of-defocus sensitive manner, while VIP is the principal neurotransmitter of the VIPergic amacrine cells of the retina, which were shown to be involved in myopia development." (PMID 34107987, 2021). "EGR1, JUN, FOS and VIP are unlikely to be important in predisposing humans to high myopia." (PMID 23637909, 2013). "Notably, Egr1, the most abundantly expressed IETF at the mRNA level which also upregulates at the protein level at 6 h PCS, is a negative regulator of myopia whose expression upregulates in the lens following selenite stress as well as Hsf4 and β1-integrin gene deletion." (PMID 36359852, 2022). "To date, the roles of EGR-1 and OPN5 in the progression of experimental myopia have not been clearly reported." (PMID 37857760, 2023). "In summary, although the therapeutic roles of EGR-1 and OPN5 have been reported in experimental myopia progression and VL research, their links have not yet been clearly determined." (PMID 37857760, 2023).
renal fibrosis (28 papers, 2013 to 2025). A final common manifestation of a wide variety of chronic kidney diseases characterized by glomerulosclerosis and tubulointerstitial fibrosis. "The transcription factor EGR1, which is expressed in several renal cell populations, has been shown to be associated with renal fibrosis and inflammation as well as being a transcriptional activator of NOX4 in DKD." (PMID 38671844, 2024). "Upregulation of Egr1 is associated with renal fibrosis and inflammation, especially in the development of diabetic nephropathy." (PMID 31392215, 2019). "A recent report has revealed that Egr1 expression is up-regulated in renal tubular cells in patients with renal failure; in turn, an Egr1 deficiency in mice protects from renal fibrosis induced by an adenine-rich diet." (PMID 28859164, 2017). "Multiple mechanisms are involved in the actions of Egr1 in diabetes mellitus-associated renal fibrosis, including elevating the expression of TGF-β, promoting the proliferation of mesangial cells, and accelerating the EMT process of renal tubular epithelial cells." (PMID 37396169, 2023). "Egr1 has also been shown to lead to upregulation of oxidative stress levels and has been associated with a variety of adverse outcomes, such as myocardial fibrosis, renal fibrosis, pulmonary hypertension, and arrhythmia after myocardial infarction." (PMID 35799890, 2022). "Besides, Egr1 is associated with the development of renal fibrosis." (PMID 37396169, 2023). "For approved medications, only a peroxisome proliferator-activated receptor-γ agonist pioglitazone improves TGF-β induced renal fibrosis with synchronized lowered EGR1 expression." (PMID 37596660, 2023). "The genetic overexpression of TGF-β in mice induces renal fibrosis through the upregulation of Egr1, STAT3, and AP-1." (PMID 37373116, 2023). "While in basic research, a DNA enzyme targeting Egr1 was reported to ameliorate renal fibrosis in unilateral ureteral obstruction rat." (PMID 37596660, 2023). "Research has shown that attenuation of TGF-β1, UUO and I/R treatment-induced renal fibrosis through MBD2 silencing or PT-MBD2-KO is due to MBD2 directly leading to increased expression of EGR1 and inducing hypomethylation in the promoter region." (PMID 37742034, 2023). "High-fiber diet: Restore gut microbiome, reduce renal fibrosis, cardiac fibrosis, and left ventricular hypertrophy via inhibiting Egr1." (PMID 35370631, 2022). "Egr1 is involved in regulating chronic hypoxia-induced renal fibrosis by targeting the PKC/ERK pathway." (PMID 35890132, 2022). "Acetate was reported to reduce BP, LVH, cardiac fibrosis, and renal fibrosis through downregulation of Egr1 in hypertensive mice." (PMID 33614542, 2020). "The miR181 was identified as an inhibitor of renal fibrosis via Egr1 inhibition, which suppressed the expression levels of alphaSMA (ACTA2), connective tissue growth factor (CTGF), collagen type I (COL1A1), and type III collagen (COL3A1) in NRK49F cells." (PMID 32121305, 2020). "Egr1 plays a key role in glucose-induced proliferation and renal fibrosis by regulating the expression of extracellular matrix genes in mesangial cells." (PMID 30770784, 2019). "Oral administration of PPARγ agonist pioglitazone significantly reduces TGF-β1-driven renal fibrosis, via the attenuation of EGR-1, STAT3 and AP-1." (PMID 31277592, 2019). "Considering the important role of Egr-1 in organ fibrosis process, it is necessary to clarify the direct mechanism of metformin in preventing renal fibrosis." (PMID 30050950, 2018). "The miR-181a family mediates renal fibrosis development and cancer progression by targeting Egr1." (PMID 35890132, 2022). "Inhibition of MAPK/ERK downregulates the expression of maladaptive tubular EGR1 and FGF2, improving renal fibrosis and renal function." (PMID 40827445, 2025). "It was consistent with the PCR results that EGR1 and PLA2G4A have the higher protein expression in the tissues of renal fibrosis as validated by the Western blot analysis." (PMID 36120336, 2022).
renal fibrosis (continued). "We found that SLC4A1, THY1, and GHR were significantly under-expressed in renal fibrosis, and PLA2G4A and EGR1 were significantly over-expressed compared with the normal group." (PMID 36120336, 2022). "The expression levels of both predictive signature genes EGR1 and PLA2G4A were validated in renal fibrosis and adjacent normal tissues by using the qRT-PCR and Western blot methods." (PMID 36120336, 2022). "Our results revealed that, compared with normal tissues, the EGR1 and PLA2G4A genes have higher expressions in tissues of renal fibrosis (p < 0.05)." (PMID 36120336, 2022). "Finally, the expression levels of both predictive signature genes EGR1 and PLA2G4A were validated in renal fibrosis and adjacent normal tissues by using qRT-PCR and Western blot method." (PMID 36120336, 2022). "Interestingly, pioglitazone has been shown to repress Egr1 transcription and traduction in kidneys of TGF-β-driven renal fibrosis in mice and in pancreas of a cerulein-induced acute pancreatitis mouse model." (PMID 32121305, 2020). "Here, we aimed to study whether the chronic administration of PPARγ agonist pioglitazone could influence renal EGR-1, STAT3 and AP-1 expression, and ameliorate renal fibrosis in TGF-β1 overexpressing mice." (PMID 31277592, 2019). "Taken together, our data show that Egr-1 plays an important role in TGF-β1-induced EMT of renal tubular epithelial cells and metformin improves EMT while inhibiting Egr-1, which provides a potential novel target to combat renal fibrosis." (PMID 30050950, 2018). "Early growth response 1 (Egr1) has been demonstrated to participate in fibrosis progression by interacting with the growth factor β (TGF-β)/Smad-dependent signaling pathway, which has a major role in the development of renal fibrosis and the inflammatory response in DKD." (PMID 38275604, 2024). "The expression levels of both EGR1 and PLA2G4A were detected in renal fibrosis and adjacent normal tissues by qRT-PCR and Western blot method." (PMID 36120336, 2022).